GRAMD4 (GRAM domain containing 4)
Description:
Inhibits TLR9 response to nucelic acids and regulates TLR9-mediated innate immune response (By similarity).
Synonyms: DIP; KIAA0767
Tractability: Antibody: UniProt predicts a signal peptide or a membrane-spanning region. PROTAC: ubiquitination databases record sites on it; its protein half-life has been measured.
Gene: Protein-coding gene on chromosome 22 (46,575,644 to 46,679,790, forward strand). Ensembl gene ENSG00000075240.
Subcellular location: Mitochondrion membrane; Endoplasmic reticulum membrane
Gene Ontology:
Molecular function: protein binding
Biological process: positive regulation of apoptotic process; negative regulation of toll-like receptor 9 signaling pathway; apoptotic process
Cellular component: mitochondrion; endoplasmic reticulum membrane; mitochondrial membrane
Genetic constraint (gnomAD): Loss-of-function variants: 19 observed, 60.72 expected, observed/expected ratio (o/e) 0.31, 90% interval 0.22 to 0.46. The upper end of that interval is the gene's LOEUF score, 0.46, which puts it in group 2 of 6, group 1 being the genes least tolerant of losing a copy. Missense variants: 542 observed, 709.95 expected, observed/expected ratio (o/e) 0.76, 90% interval 0.71 to 0.82. Synonymous variants: 293 observed, 291.99 expected, observed/expected ratio (o/e) 1, 90% interval 0.91 to 1.11.
Homologues: Orthologues: dog GRAMD4 (95% identical), macaque GRAMD4 (95% identical), rat Gramd4 (95% identical), mouse Gramd4 (94% identical), guinea pig GRAMD4 (93% identical), chimpanzee GRAMD4 (93% identical), pig GRAMD4 (93% identical), rabbit GRAMD4 (85% identical), tropical clawed frog gramd4 (81% identical), zebrafish gramd4a (73% identical), zebrafish gramd4b (73% identical).
Diseases named in the same sentence as GRAMD4 in open-access papers:
GRAMD4 is named in the same sentence as 16 diseases in open-access papers, as found by Europe PMC text mining. Sharing a sentence is not in itself a finding about the gene and the disease. The quoted sentences say what the papers report.
Macrocephaly (2 papers, 2023 to 2025). Occipitofrontal (head) circumference greater than 97th centile compared to appropriate, age matched, sex-matched normal standards. "Interestingly, several genes within Region 2, including CERK, TBC1D22A, CELSR1, and GRAMD4 were found to be implicated in seizures, renal abnormalities, lymphedema, macrocephaly, and developmental delay in PMS." (PMID 40429797, 2025). "A genomic region on 22q13.31 was found to be significantly associated with macrocephaly with CELSR1, GRAMD4, and TBCD122 suggested as candidate genes." (PMID 36980813, 2023). "There are three genes that are proposed as the main candidates for macrocephaly (TBC1D22A, CELSR1, and GRAMD4) given their location in the highly associated genomic regions, proposed function, or high probability of loss of function intolerance." (PMID 36980813, 2023). "Regarding some functionality of these genes (TBC1D22A, CELSR1, and GRAMD4), we propose previously a region of 4.5 to 8 Mb from the telomere, strongly associated with macrocephaly in PMS, also supported by this study, and aligned with other works, suggesting to GRAMD4 associated with macrocephaly." (PMID 40429797, 2025).
breast carcinoma (1 paper, 2022). "Among these six genes, five were hypermethylated (GABRA5, ZIC5, GRAMD4, RSPH3, and VCAN), and one was hypomethylated (CSMD1) in breast cancer samples of cases compared to controls." (PMID 36627894, 2022).
glioblastoma (1 paper, 2021). The most malignant astrocytic tumor (WHO grade IV). "In addition, TAK1 protein expression was negatively correlated with GRAMD4 in GBM (glioblastoma multiforme), LIHC, PAAD and UCEC." (PMID 34841685, 2021).
hepatocellular carcinoma (1 paper, 2021). A malignant tumor that arises from hepatocytes.
lung squamous cell carcinoma (1 paper, 2021). "According to previous studies, the expression of GRAMD4 was elevated in lung squamous cell carcinoma, and high GRAMD4 expression predicted poor clinical outcomes." (PMID 34841685, 2021).
lymphedema (1 paper, 2025). Excess fluid collection in tissues, causing swelling. "GRAMD4 regulates apoptosis and is linked to seizures, lymphedema, and sensory processing dysfunction." (PMID 40429797, 2025). "This study refines genotype–phenotype correlations for seizures, renal anomalies, and lymphedema, particularly in relation to deletions involving CELSR1 and GRAMD4." (PMID 40429797, 2025). "Additionally, renal abnormalities and lymphedema were significantly more prevalent among patients with deletions encompassing the CELSR1 and GRAMD4 genes (χ2 = 18.734; degrees of freedom = 2; p < 0.001)." (PMID 40429797, 2025).
Sleep apnea (1 paper, 2017). An intermittent cessation of airflow at the mouth and nose during sleep is known as sleep apnea. "Suggestive associations of symptoms of sleep apnea were observed with 11 rare variants (located in KANK2, LCN6, TRAF3, PLEK, HIF1A, SLC45A3, ERCC1/CD3EAP, MRGPRE, GRAMD4, TYW5, CST5)." (PMID 29093733, 2017).
tumour (3 papers, 2018 to 2025). "GRAMD4 is a membrane protein known to be a tumor suppressor in apoptotic pathways associated with mitochondria." (PMID 29720394, 2018). "Conversely, the downregulation of GRAMD4 inhibited tumour progression by inducing mitochondrial apoptosis." (PMID 41249152, 2025). "In our research, the proteomics data implied that the protein abundance of GRAMD4 was lower in the tumour tissues of COAD, HNSC, LIHC, LUSC and OV, but it was elevated in the tumour tissues of KIRC, LUAD, PAAD and UCEC." (PMID 34841685, 2021). "Taken together, our data demonstrate that GRAMD4 acts as a tumour suppressor by inhibiting the TAK1/MAPK axis in HCC." (PMID 34841685, 2021). "To further explore the effects of GRAMD4 on tumour growth and metastasis in vivo, we used a tail vein injection mouse model." (PMID 34841685, 2021). "As predicted, TAK1 expression was higher in the tumour tissues than in the adjacent non‐tumour liver tissues, and it was negatively correlated with GRAMD4 (r = −0.3754, p < 0.0001, Pearson correlation)." (PMID 34841685, 2021). "Moreover, correlation analysis revealed that GRAMD4 protein abundance was negatively correlated with TAK1 in the HCC tumour samples (r = −0.4282, p < 0.01, Pearson correlation)." (PMID 34841685, 2021). "Furthermore, we explored the protein abundance of GRAMD4 in other tumour types, as well as the correlation between the protein abundance of TAK1 and that of GRAMD4." (PMID 34841685, 2021). "However, there are few studies on the role of GRAMD4 in tumours." (PMID 34841685, 2021). "Furthermore, the reduced levels of L-lactic acid slow tumour progression through histone H4K16 lactylation and regulate the expression of the BEST1, GRAMD4, and MBD6 genes, with this mitochondrial effector serving as an apoptotic signal induced by E2F1." (PMID 41249152, 2025).
cancer (2 papers, 2015 to 2021). A tumor composed of atypical neoplastic, often pleomorphic cells that invade other tissues. "Since TAK1 is an important kinase of the NF‐κB and MAPK pathways, which plays crucial roles in cancer growth and metastasis, we examined the phosphorylation of p65 and several MAPKs in cell lines with GRAMD4 overexpression or knockdown." (PMID 34841685, 2021).
GRAMD4 also shares sentences with these, for which no sentence is quoted: asthma (1 paper); Cirrhosis (1); developmental delay (1); microcephaly (1); nasopharyngeal carcinoma (1); renal cell carcinoma (1); viral infection (1).